HMGA1 (high mobility group AT-hook 1)
Diseases named in the same sentence as HMGA1 in open-access papers (continued):
Sharing a sentence is not in itself a finding about the gene and the disease.
vitiligo (1 paper, 2025). Generalized well circumscribed patches of leukoderma that are generally distributed over symmetric body locations and is due to autoimmune destruction of melanocytes. "In summary, we identified two vitiligo-associated genes, HMGA1 and PSMD13, via WGCNA and machine learning approaches on datasets GSE80009 and GSE90880." (PMID 40443672, 2025). "This study identified PSMD13 and HMGA1 as potential hub genes linked to vitiligo using integrated bioinformatics and experimental validation." (PMID 40443672, 2025). "Our work underscores the importance of HMGA1 and PSMD13 in the pathophysiological mechanisms underlying vitiligo, potentially opening new avenues for both diagnostic and treatment strategies for this condition." (PMID 40443672, 2025). "Our results suggest that in vitiligo, the abnormal expression of HMGA1 may lead to changes in the function of pigment cells, increasing their vulnerability to attack by immune cells or triggering an autoimmune response, thus exacerbating vitiligo." (PMID 40443672, 2025). "Our study explored the potential of HMGA1 and PSMD13 as markers for vitiligo; these results validate our findings and have practical implications for the diagnosis and treatment of vitiligo." (PMID 40443672, 2025). "Despite their potential importance, research into the specific functions of HMGA1 and PSMD13 within the context of vitiligo remains scarce." (PMID 40443672, 2025). "The expression levels of the overlapping hub genes HMGA1 and PSMD13 in the peripheral blood of vitiligo patients and control patients were assessed via qRT–PCR." (PMID 40443672, 2025). "This study identified two key genes, HMGA1 and PSMD13, in the blood of vitiligo patients using bioinformatics and machine learning techniques." (PMID 40443672, 2025). "The changes in HMGA1 expression in the inflamed skin of vitiligo patients compared with that in healthy skin were not significant, but PSMD13 expression showed a significant downwards trend." (PMID 40443672, 2025). "In addition, PSMD13 significantly decreased in the lesioned skin of vitiligo patients, suggesting that PSMD13 is involved in the skin lesion development process through the NOD-like-receptor signalling pathway, but HMGA1 did not significantly decrease in the lesioned skin." (PMID 40443672, 2025).
vulva tumors (1 paper, 2015). "We report a detailed study of 25 vulva tumors [22 SCC, 2 MM, 1 atypical squamous cell hyperplasia (AH)] analyzed for expression of the high-mobility group AT-hook family member genes HMGA2 and HMGA1, for mutations in the IDH1, IDH2 and TERT genes, and for methylation of the MGMT promoter." (PMID 25823555, 2015).
cancer (234 papers, 2000 to 2026). A tumor composed of atypical neoplastic, often pleomorphic cells that invade other tissues. "Together, these results indicate that promoter hypomethylation underlies HMGA1 activation in a subset of cancers." (PMID 41463532, 2025). "Similar to many pluripotency factors and other “epigenetic mediators”, HMGA1 genes are highly overexpressed in diverse cancers, although they are less frequently mutated, particularly within the coding regions." (PMID 40076747, 2025). "While reduced cancer cell characteristics were clearly associated with reduced HMGA1 protein levels, the molecular pathways affected by HMGA1 sequestration or suppressed expression have not been determined." (PMID 41183073, 2025). "We observed that high HMGA1 expression was negatively associated with stromal and immune scores in many cancers, suggesting its involvement in generating an immune-excluded tumor microenvironment." (PMID 41463532, 2025). "HMGA1, a chromatin-binding protein, is implicated in transcriptional regulation and cancer progression." (PMID 40683881, 2025). "Namely, the C-terminal tail of HMGA1—a region associated with cancer aggressiveness —is phosphorylated by CK2." (PMID 41145488, 2025). "Prior studies also identified HMGA2 germline variants linked to cancer predisposition and acquired genomic lesions in HMGA1 or HMGA2 linked to myeloid malignancy." (PMID 40076747, 2025). "To identify mechanisms underlying HMGA1 upregulation in cancer, we first examined promoter methylation across TCGA tumors." (PMID 41463532, 2025). "Further research is needed to determine the complex process by which HMGA1 sequestration reduces HMGA1 protein levels and causes cancer cell death." (PMID 41183073, 2025). "Mechanistically, our comprehensive transcriptional analysis revealed that LUCAT1 significantly upregulates HMGA1 expression, a key regulatory gene associated with cancer stem cell properties." (PMID 40025525, 2025). "High mobility group A1 (HMGA1) is a chromatin-associated protein that regulates transcription and drives cancer progression." (PMID 41463532, 2025). "HMGA1 is normally overexpressed in cancer and its high levels have been associated with tumorigenic processes in various tumors, including STS." (PMID 38758230, 2024). "HMGA1 overexpression is a hallmark of human cancers and exhibits a pivotal role in cell transformation." (PMID 36820066, 2023). "The high mobility group AT-hook 1 (HMGA1) gene encodes a chromatin-associated protein that regulates gene transcription and metastatic progression in cancer cells." (PMID 36635290, 2023). "Similar to pluripotency factors, HMGA1 is rarely mutated, but almost universally overexpressed in aggressive cancers, consistent with a fundamental role in tumorigenesis." (PMID 36919699, 2023). "In this study, we performed a prognostic analysis and showed that high level of either HMGA1 or FOXM1 was associated with poor prognosis in various cancers based on the TCGA database." (PMID 37240870, 2023). "PLAU encodes a secreted urokinase associated with cancer progression/metastasis via upregulation by the AT hook factor, HMGA1." (PMID 35061738, 2022). "For many malignant neoplasms, the HMGA1 gene has been associated with a high degree of malignancy, resistance to chemotherapy, metastatic tendency, and low patient survival." (PMID 35805937, 2022). "Recent studies have revealed that HMGA1 is associated with various types of cancers including breast, lung, and colorectal cancer types." (PMID 35205612, 2022). "The lead SNP rs2780226 in HMGA1 encodes a chromatin-associated protein that regulates gene transcription and metastatic progression of cancer cells and has been associated with body height, BMI-adjusted waist circumference, and birth weight." (PMID 35831902, 2022). "Taken together, the deregulation of HMGA1 expression appears to be a hallmark of cancer and implies that HMGA1 plays an essential role in carcinogenesis." (PMID 35805937, 2022).
cancer (continued). "HMGA1 has been found to associate with tumor invasion in several cancers, which was also observed in HCC based on its significantly positive correlation with MMP9 (PCC > 0.6)." (PMID 36132143, 2022). "Transcriptional regulatory networks indicated HMGA1 as the top-ranked regulator of up-regulated TFs, which promotes epithelial-to-mesenchymal transition in cancer and associated with PAH; NFIX is the top-ranked regulator of down-regulated TFs." (PMID 36303246, 2022). "Although the role of HMGA2 in the metastasis and growth of malignant tumors in the esophagus, stomach, and colorectum has been examined, the role of HMGA1 and its underlying mechanism remain poorly understood." (PMID 35629376, 2022). "Exosome-induced overexpression of HMGA1 causes a number of changes in cancer cells, including the intensification of proliferation, migration, and invasion, and changes in the activity of tissue architecture maintenance proteins." (PMID 36139487, 2022). "Accordingly, studies using tumor tissue specimens revealed that high HMGA1 expression is associated with a poor differentiation state and advanced disease or high-grade cancers." (PMID 35049679, 2021). "The gene encoding the High Mobility Group A1 (HMGA1) chromatin remodeling protein is upregulated in diverse cancers where high levels portend adverse clinical outcomes." (PMID 34572547, 2021). "Because HMGA1 is linked to EMP in cancer and development, it is plausible that crosstalk between the nuclear and the extracellular forms of HMGA1 occur with plasticity." (PMID 34572547, 2021). "The re-expression of HMGA1 in adults has been associated with the onset of diseases, including diabetes and cancer." (PMID 31779212, 2019). "Nevertheless, if the secretion of HMGA1 in these cancer types is associated with tumor invasion, the onset of metastasis remains to be defined." (PMID 31779212, 2019). "Mechanistically, we show that NOTCH signalling represses the chromatin architectural protein HMGA1, an association found in multiple human cancers." (PMID 29743479, 2018). "Biologically, HMGA1 encodes a protein that is functionally associated with chromatin, which is involved in the metastatic progression of cancer cells." (PMID 28830341, 2017). "Abnormally high expression rates of HMGA1 constitute a hallmark for the vast majority of cancers and generally correlate with a poor outcome." (PMID 26117853, 2015). "The variation in EMT genes modulated by HMGA1 in these two different cell lines likely reflects the differing milieu and reprogramming potential in the cancer cells based on underlying genetic and epigenetic changes." (PMID 22276142, 2012). "Notably, ESCA displayed a distinct expression profile, with HMGA1 detected in malignant epithelial cells, cancer-associated fibroblasts, and CD8+ exhausted T cells." (PMID 41463532, 2025). "The precise mechanism by which HMGA1 sequestration reduced HMGA1 protein levels and caused increased cancer cell death remains unclear." (PMID 41183073, 2025). "Consistent with an epigenetically permissive promoter, DNase-seq profiles from ENCODE showed increased chromatin accessibility at the HMGA1 promoter across ten cancer types, supporting a model in which promoter hypomethylation facilitates transcriptional activation." (PMID 41463532, 2025). "Interestingly, in some cancer types where HMGA1 expression showed a positive association with immune scores, patients still exhibited poor prognosis." (PMID 41463532, 2025). "Notably, HMGA1 showed a consistent positive association with the activation of regulatory T cells (Tregs) in several cancers, including BRCA, GBM, and LIHC." (PMID 41463532, 2025). "However, HMGA1 is re‐expressed in cancer cells and cancer stem cells, where it is associated with enhanced metastasis and poor clinical prognosis." (PMID 39690136, 2024).
cancer (continued). "Notably, the transcriptional regulator most associated with GPCR deregulation is HMGA1, a chromatin protein that was reported to promote cancer aggressiveness in part via Wnt signaling amplification." (PMID 38723607, 2024). "Furthermore, liver metastases also exhibited higher expression levels of a variety of cancer cell-associated genes (such as Hmga1 and Grem1) compared to primary tumors." (PMID 37190324, 2023). "In addition, HMGA1 also affects the ageing, apoptosis, autophagy and chemotherapy resistance of cancer cells, which are linked to tumorigenesis." (PMID 35864955, 2022). "Increased expression of HMGA1 has been associated with uncontrolled cell growth and proliferation, cell invasion, resistance to chemotherapy, maintenance of stem-like properties and metastatic spread in many human cancers, including male GCTs." (PMID 36506071, 2022). "Further research showed that growth factors, cancer-associated mutations (KRAS, mutated APC), or cancer-related transcription factors (cMYC) could up-regulate HMGA1 in specific contexts." (PMID 35805937, 2022). "Interestingly we found that FOXP1 and CAV1, genes that are commonly repressed by HMGA1 in cancer, were positively associated with HMGA1-lnc expression." (PMID 33505435, 2020). "This may indicate that HMGA1-lnc expression is able to have the opposite effect on these cancer-associated transcriptional networks." (PMID 33505435, 2020). "In this review, we had first summarized the highlights of our recent work, and then we had hypothesized about the cancer diagnostic and therapeutic implications of the extracellular function of HMGA1." (PMID 31779212, 2019). "Cancer cells from KPHetCT;Hmga2+/+ and KPHetCT;Hmga2CK/CK mice express Hmga1 at similar levels, therefore Hmga1 could compensate for Hmga2 deficiency to enable malignant transformation and metastasis." (PMID 30228296, 2018). "Our primary aim was to exploit this cellular model to search for HMGA1–linked secreted molecules influencing cell motility/invasiveness that could be involved in conferring cancer cells metastatic abilities." (PMID 28924209, 2017). "To determine whether additional mechanisms to dysregulation, we evaluated more genomic and epitranscriptomic features through Copy number variation (CNV) analysis that revealed HMGA1 amplification occurs across several cancers and is strongly associated with increased expression." (PMID 41463532, 2025). "Based on literature reviews, HMGA1, a chromatin-binding protein, has been linked to enhanced Wnt signaling in both intestinal stem cells and cancer stem cells 38, suggesting that TOX's oncogenic activity could involve chromatin interactions and stemness regulation." (PMID 40303305, 2025). "HMGA1 is abundantly found in the nucleus and it has been implicated in numerous malignant processes, such as cell proliferation, invasion, migration and metastasis, transcriptional dysregulation, unpaired DNA damage repair mechanisms and cancer stem cell (CSC) maintenance." (PMID 38758230, 2024). "While restoration of HMGA1 in BC from COPD smokers may at first be an attractive therapeutic concept, previous studies have shown that the over-expression of HMGA1 is associated with cancer, suggesting there may be unfavorable off-target effects of HMGA1 over-expression in BC." (PMID 29581847, 2018). "High mobility group AT-hook 1 (HMGA1) is a chromatin regulator overexpressed in various cancers, often predicting poor outcomes." (PMID 41943828, 2026). "Collectively these findings indicate that HMGA1 orchestrates a versatile oncogenic program, utilizing common proliferation and metabolic programs across cancers while modulating context-specific pathways to support tumor survival and progression." (PMID 41463532, 2025). "In this pan-cancer study, we analyzed multi-omics data to comprehensively characterize HMGA1’s expression patterns, prognostic significance, epigenetic regulation, and immunotherapy roles." (PMID 41463532, 2025).
cancer (continued). "HMGA1 represents a viable target for immunotherapy, and our cancer model derived from this subpopulation offers prognostic significance and direction for immunotherapeutic treatments." (PMID 40842994, 2025). "By analyzing data from thousands of patients across numerous cancer types, we discovered that HMGA1 is frequently overactive due to specific chemical changes on its DNA." (PMID 41463532, 2025). "Since HMGA1 cannot be targeted using conventional small molecule drug therapy, alternative approaches are needed to target HMGA1 in new cancer therapies." (PMID 41183073, 2025). "HMGA1 plays a critical role in both tumour initiation and progression, and it also acts as a key regulator of autophagy pathways in cancer cells, contributing to tumour development." (PMID 39828988, 2025). "Analysis of the HMGA family transcriptional landscape across 33 TCGA cancers revealed that HMGA1 displayed the highest median expression and broadest distribution among all HMG members." (PMID 41463532, 2025). "In this project, three different engineered adenovirus vectors designed to suppress oncogenic HMGA1 activity in human cancer cells were developed and tested." (PMID 41183073, 2025). "Machine learning analysis pinpointed 14 feature genes, among seven were associated with cancer (NAT1, BIRC3, EZH2, MAD2L1, ATP2A3, HMGA1, and BST2)." (PMID 41255601, 2025). "Crucially, quantitative analysis confirmed that all six cancer types, Tregs consistently maintained HMGA1 expression exceeding log-normalized level of 2, representing one of the most reliably high-expressing immune populations." (PMID 41463532, 2025). "Conversely, HMGA1 depletion not only suppresses cancer cell proliferation but also triggers programmed cell death, increasing the sensitivity of cancer cells to chemotherapy." (PMID 41145488, 2025). "In this study, we investigated a protein called HMGA1, which is known to be present in high amounts in many cancers but whose broader role was not fully understood." (PMID 41463532, 2025). "In summary, our comprehensive pan-cancer analysis defines HMGA1 as a master oncogenic regulator whose influence extends from genetic and epitranscriptomic regulation to the control of the tumor immune landscape." (PMID 41463532, 2025). "HMGA1 is expressed at low levels in normal tissues but is highly expressed in a variety of malignant tumors, including breast, liver, lung, bladder, and ovarian cancers." (PMID 40288645, 2025). "Our pan-cancer analysis establishes the architectural transcription factor HMGA1 as a critical node at the intersection of these processes." (PMID 41463532, 2025). "Pan-cancer profiling showed that HMGA1 is broadly overexpressed and clinically relevant across multiple tumor types." (PMID 41463532, 2025). "More intriguingly, we discovered that HMGA1 expression shows widespread positive correlations with regulators of key RNA modifications, including m6A, m5C, and m1A, across diverse cancer types." (PMID 41463532, 2025). "HMGA1 expression was positively correlated with both tumor mutational burden (TMB) and microsatellite instability (MSI) in numerous cancers." (PMID 41463532, 2025). "In breast cancer cells, circPLK1 regulates the miR-1294/HMGA1 axis, resulting in reduced cancer cell migration, invasion, and tumor stemness, despite its usual oncogenic role in other cancers." (PMID 40740236, 2025). "HMGA1 is a transcription factor involved in several cellular processes and found to be upregulated in different tumors, but its extracellular role in cancer remains largely unexplored." (PMID 41145488, 2025). "While prior studies have established HMGA1’s pro-tumorigenic functions within specific cancer types, the field still lacks a unified investigation that defines its overarching role across human malignancies." (PMID 41463532, 2025). "In closing, emerging evidence focused on chromatin regulators, such as HMGA1, illuminates the epigenome as our next frontier in cancer biology and therapeutics." (PMID 40076747, 2025).